ZMAT5 (zinc finger matrin-type 5)
Synonyms: U11/U12-20K; SNRNP20; ZC3H19
Tractability: Small molecule: a structure with a bound ligand is known. PROTAC: ubiquitination databases record sites on it.
Gene: Protein-coding gene on chromosome 22 (29,728,138 to 29,767,084, reverse strand). Ensembl gene ENSG00000100319.
Subcellular location: Nucleus
Subcellular location (Human Protein Atlas): Nucleoplasm
Pathways (Reactome):
Metabolism of RNA: mRNA Splicing - Minor Pathway
Gene Ontology:
Molecular function: protein binding; metal ion binding; zinc ion binding
Biological process: mRNA splicing, via spliceosome; RNA splicing; spliceosome conformational change to release U4 (or U4atac) and U1 (or U11)
Cellular component: nucleoplasm; spliceosomal complex; U11/U12 snRNP; U12-type precatalytic spliceosome; U12-type spliceosomal complex; nucleus
Genetic constraint (gnomAD): Loss-of-function variants: 23 observed, 24.44 expected, observed/expected ratio (o/e) 0.94, 90% interval 0.68 to 1.33. The upper end of that interval is the gene's LOEUF score, 1.33, which puts it in group 5 of 6, group 1 being the genes least tolerant of losing a copy. Missense variants: 173 observed, 198.72 expected, observed/expected ratio (o/e) 0.87, 90% interval 0.77 to 0.99. Synonymous variants: 76 observed, 72.06 expected, observed/expected ratio (o/e) 1.05, 90% interval 0.88 to 1.28.
Homologues: Orthologues: chimpanzee ZMAT5 (100% identical), guinea pig ZMAT5 (95% identical), pig ZMAT5 (94% identical), mouse Zmat5 (93% identical), rat Zmat5 (93% identical), macaque ZMAT5 (81% identical), rabbit ZMAT5 (81% identical), zebrafish zmat5 (49% identical), tropical clawed frog zmat5 (40% identical), Drosophila melanogaster CG31922 (27% identical).